VKORC1 (vitamin K epoxide reductase complex subunit 1)
Diseases named in the same sentence as VKORC1 in open-access papers (continued):
Sharing a sentence is not in itself a finding about the gene and the disease.
coronary heart disease (3 papers, 2008 to 2020). "Thus, we have documented that CYP4F2 and VKORC1 polymorphisms boost the proinflammatory plaque environment (observed indirectly through the presence of ischemic heart disease), increasing the risk of plaque development." (PMID 32698322, 2020). "In light of this, our findings emphasizing the effect of VKORC1 and CYP4F2 on increasing the risk of plaque development once ischemic heart disease is already present are noteworthy." (PMID 32698322, 2020). "We further observed that VKORC1 interacted with the presence of ischemic heart disease only in the case of carotid or any of the two plaques." (PMID 32698322, 2020).
melanoma (3 papers, 2022 to 2024). A malignant, usually aggressive tumor composed of atypical, neoplastic melanocytes. "Such examples include the prescription of vemurafenib to melanoma patients carrying the BRAF V600E or warfarin and clopidogrel (Plavix) drugs prescribed for cardiovascular disease-treatment, the response of which is affected by genetic polymorphisms (VKORC1, CYP2C9 and CYP2C19 genes)." (PMID 35260588, 2022). "The most significant differences in melanoma are NOMO1, PIGT, VKORC1, PDIA5 and DDX11, and the most significant differences in uterine cancer are CTU2, EMC8, TUBG1, CLPP and LONP1." (PMID 34951103, 2022).
thrombophilia (3 papers, 2018 to 2019). A condition characterized by an abnormally high level of thrombi. "We evaluated the relationship between warfarin doses clinically determined according to INR and age, gender, body mass index, indication for the warfarin therapy, statins use, inherited thrombophilia and VKORC1, CYP2C9*C2 and CYP2C9*C3 gene polymorphisms." (PMID 31531081, 2019).
thrombosis (3 papers, 2009 to 2022). "We also analysed the CYP2C9 (C430T, A1075C) and VKORC1 (G1639A) variants in fifty-eight individuals with predisposition to thrombosis (possessing at least one variation in F5 or F2 genes and one in MTHFR) to evaluate their warfarin drug response genetic profiles." (PMID 19538716, 2009).
triple-negative breast carcinoma (3 papers, 2019 to 2023). An invasive breast carcinoma which is negative for expression of estrogen receptor (ER), progesterone receptor (PR), and human epidermal growth factor receptor 2 (HER2). "The highest expressions of GGCX and VKORC1 have been observed in triple negative breast cancer cell lines and in advanced stages of disease, such as invasive breast cancers, when compared with normal mammary glands." (PMID 37670241, 2023). "qPCR results indicated highest expression of GGCX, VKORC1, and VKORC1L1 in triple negative breast cancer (TNBC) cell lines, Hs578T, MDA-MB-231 and SUM159PT, and in advanced stage disease." (PMID 31040920, 2019).
Alzheimer disease (2 papers, 2021 to 2024). A progressive, neurodegenerative disease characterized by loss of function and death of nerve cells in several areas of the brain leading to loss of cognitive function such as memory and language. "Variation in VKORC1 has been linked in a gene-based test to dementia/Alzheimer’s disease in the parents of participants, with suggestive evidence for an association for rs9923231 (p = 1.8×10–7), which was included in the genome-wide significant KAT8 locus." (PMID 33682710, 2021).
atherosclerosis (2 papers, 2016 to 2019). A disease characterized by the build-up of fatty material and calcium deposition in the arterial wall resulting in partial or complete occlusion of the arterial lumen. "Thus, we have performed a case-control study on representatives of Ukrainian population with the aim of investigating the possible association of the VKORC1 G-1639A and C1173T SNPs with IS in individuals who had different risk factors of atherosclerosis." (PMID 27703968, 2016).
cerebrovascular disease (2 papers, 2016 to 2024). "Since the discovery of the VKORC1 gene in 2004, numerous studies about the relation of various single-nucleotide polymorphisms (SNPs) of the VKORC1 gene to development of cardiovascular and cerebrovascular diseases were conducted." (PMID 27703968, 2016). "At the same time, the most case-control studies in Europe and North America population did not reveal association between VKORC1 SNPs and cerebrovascular diseases development." (PMID 27703968, 2016).
coagulation factor deficiency (2 papers, 2017 to 2019). "Some cephalosporins with an NMTT side chain are known to cause Vit K-dependent coagulation factor deficiency by inhibiting the Vit K epoxide reductase complex subunit 1 (VKORC1)." (PMID 30805005, 2019). "Next to VKCFD1, a second autosomal recessive coagulation factor deficiency exists, VKCFD2 (OMIM#607473), caused by VKORC1 (vitamin K epoxide reductase complex, subunit 1; OMIM*608547) mutations and is also characterized by a deficiency of all VK-dependent clotting factors." (PMID 28125048, 2017).
dementia (2 papers, 2021 to 2022). Loss of intellectual abilities interfering with an individual's social and occupational functions. "We used logistic regression and data from 238,195 participants from UK Biobank to examine the relationship between VKORC1, risk of dementia, and the interplay with warfarin use." (PMID 33682710, 2021). "Within the neurodegenerative group, two proteins (VKORC1 and STX1B) were shared between AD and PD, and two other proteins (QPCT and CD2AP) were shared between the clinical diagnosis of AD and AD based on both clinical diagnosis and family history of dementia." (PMID 35882878, 2022).
intracerebral hemorrhage (2 papers, 2014 to 2020). A cerebrovascular disorder characterized by bleeding into one or both cerebral hemispheres including the basal ganglia and the cerebral cortex. "Studies confirmed that CYP2C9 and VKORC1 (vitamin K epoxide reductase complex, subunit 1) gene variants constitute strong risk factors of warfarin-related intracerebral hemorrhage." (PMID 33049931, 2020).
invasive breast carcinoma (2 papers, 2019 to 2023). A carcinoma that infiltrates the breast parenchyma. "Collectively, the available genomic and proteomic data suggest that the vitamin K-dependent pathway genes, GGCX, VKORC1, and VKORC1L1, are present in normal mammary gland but up-regulated in a subset of invasive breast cancers that are characterized by poor overall survival." (PMID 31040920, 2019).
ischemic stroke (2 papers, 2016 to 2023). A stroke disorder caused by obstruction of blood flow to the brain, due to thrombotic (local blood clot formation) or embolic (due to a blood clot or other material traveling from another site) event. "This is the first study on patients with ischemic stroke that has examined the role of polymorphisms in the VKORC1, CYP4F2, and GGCX genes together." (PMID 37653796, 2023). "For almost all variables, the presence of VKORC1 or CYP4F2 mutations significantly increased the risk of ischemic stroke." (PMID 37653796, 2023). "Herein, the association between G-1639A (rs9923231) and C1173T (rs9934438) single-nucleotide polymorphisms (SNPs) of the VKORC1 gene and ischemic stroke (IS) was tested in Ukrainian population." (PMID 27703968, 2016). "Finally, more people should be enrolled in the study even as other VKORC1 SNPs should be analyzed in order to make a definitive conclusion about VKORC1 association with ischemic stroke in Ukrainian population." (PMID 27703968, 2016). "The VKORC1 − 1639G > A polymorphism did not increase the risk of ischemic stroke in 1 study." (PMID 37653796, 2023). "Polymorphisms in the VKORC1 and CYP4F2 genes may increase the risk of ischemic stroke in patients without a determined embolic source." (PMID 37653796, 2023). "The VKORC1 rs9923231 and CYP4F2 rs2108622 polymorphisms may increase the risk of ischemic stroke in patients without a determined embolic source." (PMID 37653796, 2023).
vascular dementia (2 papers, 2021 to 2024). A degenerative vascular disorder affecting the brain. "If that is the case, then there should be an even stronger relationship between VKORC1 and vascular dementia (VaD) that is mostly due to cardiovascular factors." (PMID 33682710, 2021).
acute kidney injury (1 paper, 2023). Sudden and sustained deterioration of the kidney function characterized by decreased glomerular filtration rate, increased serum creatinine or oliguria. "In conclusion, our study provides evidence that acute kidney injury possibly interacted with VKORC1 polymorphism and this interaction significantly affected the dose of warfarin." (PMID 38066032, 2023). "In other words, when acute kidney injury and mutation of VKORC1 (1639G>A) are both present, their additive net influence on the average daily dose is significantly smaller than the arithmetic sum of the influences of each factor individually." (PMID 38066032, 2023). "The primary discovery of our study is that we observed a significant additive interaction between the occurrence of post-operation acute kidney injury and VKORC1 polymorphism." (PMID 38066032, 2023).
alcohol abuse (1 paper, 2022). The use of alcoholic beverages to excess, either on individual occasions ("binge drinking") or as a regular practice. "Third, some variables have not been collected, such as the patients’ smoking or alcohol intake and patient genotypes (VKORC1 and CYP2C9), which limited the analysis, although patients with smoking and alcohol abuse are rare in our clinical practice." (PMID 36225580, 2022).
asthma (1 paper, 2017). "The different responses with the asthma-medication salbutamol and the blood-thinner warfarin have been attributed to variants in their respective drug targets, including R16G in ADRB2 (rs1042713) for salbutamol and 1639G > A (rs9923231) in VKORC1 for warfarin." (PMID 29273096, 2017).
breast tumors (1 paper, 2019). "In addition, TCGA data indicated that the subset of patients whose breast tumors exhibit genomic amplification or up-regulation of GGCX, VKORC1, and VKORC1L1 had significantly reduced overall survival." (PMID 31040920, 2019).
calcification (1 paper, 2024). Process by which organic tissue becomes hardened by the physiologic deposit of calcium salts. "Our patients without a VKORC1 polymorphism had a lower risk of calcifications." (PMID 38674033, 2024).
gastrointestinal bleeding (1 paper, 2023). "Risk for upper gastrointestinal bleeding associated with CYP2C9 and VKORC1 genotypes and use of low-dose aspirin (LDA)." (PMID 36942299, 2023). "Risk for upper gastrointestinal bleeding associated with CYP2C9 and VKORC1 genotypes and dose of non-steroidal anti-inflammatory drugs (NSAIDs) consumed." (PMID 36942299, 2023).
Gilbert syndrome (1 paper, 2019). An autosomal recessive inherited disorder characterized by unconjugated hyperbilirubinemia, resulting in harmless intermittent jaundice. "This is the case, for example, for most low-activity CYP variants (e.g., CYPs 2B6, 2C19, 2D6, 3A4, 3A5 mostly due to aberrant splicing; Zanger and Schwab, 2013), and many established variants of clinical relevance like UGT1A1∗28 and Gilberts syndrome and VKORC1 variants in warfarin metabolism." (PMID 30766545, 2019).
hepatoma (1 paper, 2015). "This was independently confirmed by both siRNA silencing and warfarin knock-down of VKOR enzymatic activity in human hepatoma HepG2 cells after Ero1 α/β isoforms and peroxiredoxin IV (PRDX4) were first functionally silenced, demonstrating that VKORC1 alone can facilitate OPF." (PMID 26264021, 2015).
Intraventricular hemorrhage (1 paper, 2025). Bleeding into the ventricles of the brain. "Although vitamin K-dependent coagulation factor deficiency is known to be molecularly associated with mutations in the GGCX or VKORC1 genes, one study indicated that the VKORC1-wildtype type increases the risk of intraventricular hemorrhage in infants." (PMID 41361303, 2025).
Kawasaki disease (1 paper, 2019). A rare inflammatory disease characterized by an acute febrile, systemic, self-limiting, medium-vessel vasculitis primarily affecting children. "This study demonstrated that height and VKORC1 1173 and CYP2C9 genotypes significantly determine warfarin dose in Kawasaki disease in Southwest Chinese." (PMID 30121860, 2019). "This study assessed the associations of warfarin dose with genetic and non-genetic variables in children with Kawasaki disease, with appropriate control groups in order to compare genotype mutations of CYP2C9, VKORC1, and CYP4F2." (PMID 30121860, 2019). "This study aimed to determine non-genetic and genetic (CYP2C9, VKORC1, CYP4F2) factors affecting warfarin dose in Kawasaki disease." (PMID 30121860, 2019). "While the influences of CYP2C9, VKORC1, and CYP4F2 for warfarin dosage are not determinate in pediatric patients with Kawasaki disease." (PMID 30121860, 2019).
lymph node metastasis (1 paper, 2023). "In additional, Further analysis showed that VKORC1 was significantly associated with tumor size (P = 0.003), stage (P = 0,006), lymph node metastasis (P = 0.001), and APTT (P = 0.015), but not with sex (P = 0.528) and age (P = 0.681)." (PMID 37880233, 2023).
mental disorder (1 paper, 2022). A disease that has its basis in the disruption of mental process. "Of the 39 PGx drugs, nine drugs (23%) with more than one actionable DGI,including genes coding forCYP2D6, CYP2C19, HLA-A, HLA-B, CYP2C9, CYP4F2or VKORC1 were used by 3.9% of the PGx drug users of the population and9.7% of the PGx drug users of the combined mental disorders casecohorts." (PMID 34753194, 2022).
nephrolithiasis (1 paper, 2024). The presence of a calculus in the pelvis of the kidney; this is most often composed of mineral salts and proteins. "Of the patients without a VKORC1 variant (n = 172) in the study sample (n = 424), two had a history of nephrolithiasis (1.2%), which can be compared to twenty-one (9.1%) of those with a VKORC1 variant." (PMID 38674033, 2024). "We found a significant association between the VKORC1 C1173T polymorphism and nephrolithiasis in sarcoidosis patients." (PMID 38674033, 2024). "The presence of a VKORC1 C1173T variant allele was found to be a substantial risk factor for the development of nephrolithiasis in sarcoidosis patients." (PMID 38674033, 2024). "The presence of a VKORC1 variant allele may serve as a potential genetic marker of the risk of developing nephrolithiasis in conjunction with pre-existing sarcoidosis." (PMID 38674033, 2024). "Additionally, we assessed the association between a VKORC1 polymorphism implicated in the activation of proteins associated with calcification and nephrolithiasis in patients with sarcoidosis." (PMID 38674033, 2024). "This study provides novel insights into the genetic basis of nephrolithiasis in sarcoidosis patients, identifying VKORC1 C1173T as a potential contributor." (PMID 38674033, 2024). "This study provides novel insights into the genetic basis of nephrolithiasis among sarcoidosis patients, implicating VKORC1 C1173T as a potential contributor." (PMID 38674033, 2024). "This study aimed to investigate the VKORC1 C1173T polymorphism (rs9934438) in a Dutch sarcoidosis cohort, comparing individuals with and without a history of nephrolithiasis." (PMID 38674033, 2024). "This study aimed to investigate the VKORC1 C1173T polymorphism in a Dutch cohort of sarcoidosis patients, comparing individuals with and without a history of nephrolithiasis." (PMID 38674033, 2024). "Of the 424 sarcoidosis patients studied, 5.4% had a history of nephrolithiasis (Group I), only two of whom possessed no VKORC1 polymorphisms (OR = 7.73; 95% CI 1.79–33.4; p = 0.001)." (PMID 38674033, 2024). "The vitamin K epoxide reductase complex subunit 1 (VKORC1) gene, which plays a crucial role in vitamin K metabolism, has been implicated in the activation of proteins associated with calcification, including in the forming of nephrolithiasis." (PMID 38674033, 2024). "We wondered whether VKORC1 could also play a role in the formation of kidney stones in sarcoidosis, in addition to other effects." (PMID 38674033, 2024). "Also, it would be interesting to understand the VKORC1 polymorphism in patients with nephrolithiasis without sarcoidosis." (PMID 38674033, 2024).
postmenopausal osteoporosis (1 paper, 2019). Metabolic disorder associated with fractures of the femoral neck, vertebrae, and distal forearm. "A total of 150 female patients with postmenopausal osteoporosis were included in the study to investigate the relationship between postosteoporotic spinal fractures and the distribution of 9041 G/A and 3673 G/A polymorphisms in the VKORC1 gene." (PMID 30892416, 2019).
pulmonary fibrosis (1 paper, 2019). Chronic progressive interstitial lung disorder characterized by the replacement of the lung tissue by connective tissue, leading to progressive dyspnea, respiratory failure, or right heart failure. "VKORC1 (rs9923231 and rs9934438) and CYP2C9 (rs1799853 and rs1057910) were genotyped in this family, which includes a significant number of pulmonary fibrosis patients." (PMID 30866412, 2019).
cardiovascular diseases (7 papers, 2016 to 2025). "Mutation in VKORC1 associated with a limited vitamin K intake is thus a major risk for cardiovascular disease." (PMID 30214074, 2018). "Furthermore, two studies that included patients from the Chinese Han population found that VKORC1 mutations were associated with a higher risk of cardiovascular diseases, including stroke." (PMID 32071341, 2020). "Moreover, potential correlations between various VKORC1 polymorphisms and indicators of CV mortality have been reported, where several allelic variations within the VKORC1 gene were associated with arterial calcification and increased cardiovascular disease (CVD) risk." (PMID 41465069, 2025). "Single nucleotide polymorphisms (SNPs) in the VKORC1, CYP4F2, and GGCX genes have been linked to clinical outcomes, such as bleeding and cardiovascular diseases." (PMID 37653796, 2023). "For instance, in cardiovascular diseases, the probability of MACE due to clopidogrel and the efficacy of CYP2C9 and VKORC1 testing to avoid bleeding complications of warfarin mostly affected the ICER results in clopidogrel and warfarin users, respectively." (PMID 34600523, 2021).
cancer (6 papers, 2011 to 2019). A tumor composed of atypical neoplastic, often pleomorphic cells that invade other tissues. "For example, optimal warfarin dosing is known to be dependent on variants in CYP2C9 in addition to VKORC1 and variants in the ADME gene UGT1A1 are documented to contribute to different responses to the cancer drug irinotecan around the globe." (PMID 29273096, 2017). "The relevance of this pathway to cancer is of potential interest given overexpression of both Ggcx and Vkorc1 have been observed in several cancers, including both liver cancer and several adenocarcinoma’s that co-express Gas6 (Oncomine database)." (PMID 27916840, 2016). "Although VKORC1 has been studied extensively in warfarin dosing, it has an unclear role in cancer biology." (PMID 27765905, 2016).